NRP1 (neuropilin 1)
Diseases named in the same sentence as NRP1 in open-access papers (continued):
Sharing a sentence is not in itself a finding about the gene and the disease.
tumor (continued). "Our study evaluated the role of Nrp1 on tumor/self-reactive CD8+ T cells, which has previously been underexplored." (PMID 25343644, 2014). "Results from our mouse studies suggest that Nrp1 is expressed on tumor/self-reactive T cells, particularly under conditions that favor T cell dysfunction or tolerance." (PMID 25343644, 2014). "NRP-1 expression was directly correlated with myeloblast percentage in the bone marrow of patients with AML, suggesting that NRP-1 correlates with tumor load." (PMID 24385810, 2013). "Recently, NRP-1 was found to promote tumor progression by interacting with other proteins, such as integrin beta-1 and hepatocyte growth factor/scatter factor." (PMID 23251257, 2013). "In this context, it has been described that blocking Nrp-1 function reduced tumour growth by inhibition of vascular remodelling, rendering vessels more susceptible to anti-VEGF therapy." (PMID 23585849, 2013). "In one report, there was a positive trend toward increased presence of a sizable fraction of Foxp3+ cells which exhibited low expression levels of Nrp-1 in the tumor tissue of tumor-bearing mice." (PMID 23874336, 2013). "In tumor-bearing mice, Nrp-1 expression on Treg cells was demonstrated to promote their recruitment to tumor site via tumor-derived VEGF gradient." (PMID 23874336, 2013). "Pathologically, the upregulation of NRP-1 has been found in a variety of tumor cells and has been demonstrated to be involved in tumorigenesis and tumor progression." (PMID 24053763, 2013). "Knockdown of NRP-1 by the NRP-1 shRNA lentivirus led to a significant reduction of tumor MVD, significantly inhibiting the growth of HCC." (PMID 23251257, 2013). "Immunohistochemistry was performed to detect the expression of NRP-1 in tumor tissue samples from 266 NPC patients." (PMID 24053763, 2013). "The C-terminal CendR motif interacts with neuropilin-1 (NRP-1), and the NRP-1 interaction triggers the activation of a transport pathway (CendR pathway) through the vascular wall and through extravascular tumor tissue." (PMID 23986882, 2013). "We have previously shown that, similar to tumour-associated TEMs, Phd2+/− macrophages do not upregulate either Vegf or inflammatory genes, but instead express increased levels of Tie2, Nrp1, Cxcr4, Pdgfb and Sdf1, which together may enhance their proarteriogenic capacity." (PMID 23616286, 2013). "Based on this data, one possibility is that the presence of human CD4+Nrp1+CD25high T in lymph nodes cooperates with the tolerogenic microenvironment of tumor burden areas." (PMID 24324469, 2013). "Given the fact that the expression or elevation of integrin αvβ3 and neuropilin-1 are only restricted to tumors, we propose a strategy to improve the targeted delivery of Tα1 to tumor cells by adding the iRGD fragment to the C-terminus of Tα1." (PMID 23977262, 2013). "Considerable experimental evidence has shown that NRP-1 plays an essential role in the tumor growth and metastasis by regulating angiogenesis." (PMID 23251257, 2013). "Neuropilin-1 is expressed by a variety of human tumor cell types, such as breast cancer cells, melanoma, astrocytoma, and prostate carcinoma, among others." (PMID 24324469, 2013). "This is consistent with our results, which showed a relatively high loading of KDR on the principal component associated with VEGFC, NRP1, and PLXND1, which had the second highest association with triple-negative (TN) status in the all-tumor data set." (PMID 23667446, 2013). "Proteolytic processing of iRGD in tumors activates the cryptic CendR motif, which then binds to neuropilin-1 activating an endocytic bulk transport pathway through tumor tissue." (PMID 23986882, 2013). "Other strategies that use Nrp1 as an endocytic receptor to target drugs specifically to Nrp1+ cells in the tumor microenvironment also show great promise." (PMID 24386482, 2013). "Taken together, these data indicate that tumor-derived VEGF is required to attract CD4+Foxp3+Nrp1+ T cells that can support tumor growth." (PMID 24324469, 2013).
tumor (continued). "A recent study has identified differential NRP-1 expression on the surface of natural and induced Treg cells that suppress an effective anti-tumor immune response within tumor tissues." (PMID 23185562, 2012). "NRP-1 is a cell-surface receptor expressed in various cells and is also found to be overexpressed in tumor tissues." (PMID 23046982, 2012). "A significant difference existed between the expression of NRP1 in normal and tumour tissues (P<0.001)." (PMID 22926477, 2012). "In this study, we have shown that B16F10 overexpressed Sema 3A disrupts tumor-endothelial interaction through NRP1 mediated process." (PMID 22448259, 2012). "In the process of enhancing the penetration of tumor cells, the RGD motif mediates binding to αν integrins firstly on tumor endothelium followed by a proteolytic cleavage, exposing a binding motif for NRP-1, which can mediate penetration into tissue and cells." (PMID 22949871, 2012). "Multiple members of SEMA3 and Plexin plus NRP1 were already present in PanIN lesions adjacent to invasive ductal neoplastic tumor nests, suggesting that concomitant expression of SEMA3/PLXN/NRP1 occurs in the early steps of PDAC tumorigenesis." (PMID 23251334, 2012). "In the present study we have demonstrated that in HT1080 cells, hypoxia up-regulates the expression of NRP-1 in a HIF-1α-dependent manner and, more importantly, this up-regulated NRP-1 plays a deterministic role in their vasculogenic mimicry and tumour growth." (PMID 23185562, 2012). "NRP-1 expression is found to be up-regulated in multiple tumour types and correlates with tumour progression and/or prognosis in a tumour-specific manner." (PMID 23185562, 2012). "Earlier we have reported the crucial role of NRP1 in regulation of tumor endothelial interaction which ultimately regulates tumor angiogenesis." (PMID 22448259, 2012). "Conditional deletion of NRP-1 completely blocked tumor formation in the chemical carcinogenesis model compared to control mice which all developed papillomas." (PMID 23125933, 2012). "Anti-Nrp-1 in combination with anti-VEGF Ab: reduced vessel density in tumor and exhibited additive effect on tumor suppression." (PMID 24213317, 2012). "av integrin and neuropilin-1 expression is largely restricted to tumours but most importantly the response is tumour specific because the peptide cleavage will only occur if there has been prior integrin activation." (PMID 23125850, 2012). "The ability of SEMA3A to inhibit tumour angiogenesis by competing with vascular endothelium growth factor (VEGF) for binding with NRP1 has been more intensively studied and confirmed." (PMID 22926477, 2012). "The shRNA-mediated silencing of NRP-1 was found to be completely effective in abrogating the tumour growth." (PMID 23185562, 2012). "Several approaches have already been used to inhibit the NRP-1 function and, consequently block the pathological angiogenesis and tumour growth." (PMID 23185562, 2012). "The silencing of NRP-1 resulted in a complete abrogation of tumour formation, confirming its status as a promising therapeutic target for the control of tumour angiogenesis and growth." (PMID 23185562, 2012). "iRGD is a kind of tumor-penetrating peptide which can enhance the permeability of tumor cells mediated by integrins and neuropilin-1 (NRP-1) upregulated on the cells." (PMID 22949871, 2012). "Taken together our results suggested that overexpression of Sema 3A regulates tumor-endothelial cell interaction through NRP1 dependent paracrine mechanism." (PMID 22448259, 2012). "Another VEGF receptor, NRP-1 (Neuropilin 1), identified in the early nineties, was found to be expressed by the endothelial cells, vascular smooth muscle cells as well as by the tumour cells." (PMID 23185562, 2012). "Many malignant tumor cell lines express Nrp1 and/or Nrp2, and this appears to contribute to their aggressiveness." (PMID 22948112, 2012).
tumor (continued). "Immunohistochemical staining of SEMA3A and NRP1 was performed on 15 normal tongue epithelium specimens and the 43 tumour specimens." (PMID 22926477, 2012). "VEGF produced by tumor cells has been shown to act in an autocrine manner to promote cell growth through interaction with NRP-1." (PMID 23185562, 2012). "We optimized H-Ala-Thr-Trp-Leu-Pro-Pro-Arg-OH (ATWLPPR) peptide-targeted silica-based nanoparticles to target the tumor vasculature through the vascular receptor neuropilin-1 (NRP-1)." (PMID 23144911, 2012). "NRP-1 expressed on these cells regulates the immunological anti-tumor control by guiding them into the tumor in response to tumor-derived VEGF." (PMID 23185562, 2012). "For instance, we observed that LAP-β1 (RHRR CendR motif) is rapidly internalized into tumor cells after it binds to Nrp1." (PMID 22948112, 2012). "In our experiments we observed that the tumour cells themselves had acquired vascular cell-like properties in vivo as a consequence of HIF1-α-mediated up-regulation of NRP-1." (PMID 23185562, 2012). "NRP-1 expression is related to SCFA expression, but this association is lost in fields and expression becomes unlinked from EEC-like patterns in adenomatous tissue, implying an early and potential alternative role for NRP-1 in neoplasia." (PMID 21401950, 2011). "In all experiments, NRP1 seems to be essential for Sema3 A-mediated inhibition of tumor growth, angiogenesis and metastasis." (PMID 24212788, 2011). "This is because extrapolation from in vitro experiments estimates the number of NRP1 co-receptors on the tumor endothelium to be 39,500 molecules/cell, compared to the value of 100,000 molecules/cell used in Baseline Model 2, leading to more unbound VEGF." (PMID 22104283, 2011). "Use of siRNA targeting NRP1 significantly reduces tumor growth, angiogenesis, metastasis formation in various human cancer models, such as hepatocellular carcinoma, acute myeloid leukemia, lung cancer." (PMID 24212788, 2011). "VEGF treatment resulted in tumor growth and vascularization, whereas treatment with soluble NRP-1 (sNRP-1) inhibited tumor angiogenesis and growth." (PMID 24212788, 2011). "In this regard, a recent study has documented the ability of fucoidans to inhibit VEGF-induced angiogenesis and tumor neovascularization in vivo, likely through modulation of cell surface neuropilins (NRP1 or NRP2) and other VEGF receptors." (PMID 21387013, 2011). "Studies show that overexpression of NRP1 promotes, while blockade of NRP1 inhibits, tumour cell survival and migration, consistent with a pro-tumorigenic role of NRP1 and direct contribution to tumour progression." (PMID 20087344, 2010). "The studies also reveal that tumor cell-secreted PDGF is the responsible molecule for differentiation as well as for recruitment through a physical interaction with NRP-1." (PMID 20687910, 2010). "Neuropilin-1 and NRP2 are expressed in a wide variety of human tumour cell lines and implicated in the survival, migration, and invasion of tumour cells." (PMID 20087344, 2010). "Other studies have examined the roles of NRP1 in tumour cell survival and proliferation, but the role of NRP1 in tumour cell migration is less well understood." (PMID 20087344, 2010). "Several previous investigations of the role of NRP1 in tumour cells have shown NRP1 as a functional VEGF receptor." (PMID 20087344, 2010). "NRP1 staining was also determined in tumor specimens from the ARCaPM xenograft model in which ARCaPM cells were inoculated into athymic mice orthotopically, resulting in skeletal metastases with a short latency." (PMID 20085644, 2010). "Ectopic expression of NRP1 in PCa cells induced cell migration, increased tumor size and microvessel density, and inhibited apoptosis." (PMID 20085644, 2010). "Understanding the molecular basis for the chemotactic effects of VEGF in VEGFR-2-negative tumour cells, and the role played by NRP1, warrant further work." (PMID 20087344, 2010).
tumor (continued). "There is increasing evidence that NRP1 plays a direct role in tumour cell biology and becomes an attractive target for anticancer strategy." (PMID 20087344, 2010). "The possibilities are that NRP1 mediates tumour cell functions either in a VEGF-dependent manner, but independent of VEGFR-2 signalling, or via interaction with other cell-surface receptors and ligands, to transduce signalling and biological functions." (PMID 20087344, 2010). "A recent study demonstrated that PlGF, a ligand for VEGFR1 as well as Neuropilins 1 and 2 (NRP1/2), significantly modulated the recruitment of macrophages, tumor growth and local invasion." (PMID 19763275, 2009). "The receptor occupancy in the tumor with density of 10,000 NRP1 per endothelial cell is qualitatively similar to that in the healthy tissue." (PMID 18713470, 2008). "Increasing the NRP1 density in the tumor by an order of magnitude only decreases the tumor VEGF at high vascular permeability in tumor." (PMID 18713470, 2008). "VEGF164 and neuropilin-1 mRNA and protein levels are significantly higher in tumours and in GH3 tumour cell line." (PMID 18081553, 2008). "In the tumor, 41 to 68% (depending on the NRP1 density) of the VEGF population, is VEGF165 bound to the ECM while it represented only a quarter in the healthy tissue." (PMID 18713470, 2008). "Elevated expression of the VEGF165 receptor NRP1 was found in tumour cells from various human cancers." (PMID 18781179, 2008). "The elucidation of the role of NRP-1 in tumour biology remains at an early stage, but the use of NRP-1 as a prognostic factor and/or therapeutic target holds promise." (PMID 15956974, 2005). "The importance of NRP-1 as a functional receptor in neurobiology is well established, but its role in tumour biology has only recently been recognised." (PMID 15956974, 2005). "Overall, eight of 10 specimens expressed nrp-1 in the tumour epithelial cells and nine of 10 expressed EGF-R." (PMID 12618892, 2003). "It is possible that NRP-1 on tumour cells binds to VEGF-165 and acts as a carrier of VEGF to enhance VEGF binding to VEGF tyrosine kinase receptors on ECs." (PMID 12618892, 2003). "Among the poorly differentiated tumours, half of them demonstrated colocalisation of NRP-1 and EGF-R." (PMID 12618892, 2003). "Neuropilin-1 (NRP1) is overexpressed in various malignant solid tumors, modulating the tumor microenvironment (TME) via multiple mechanisms to promote immune suppression, angiogenesis, and epithelial-mesenchymal transition (EMT), ultimately resulting in poor patient survival." (PMID 41948345, 2026). "It fills the gap in the systematic summary of the NRP1-autophagy axis in regulating the dynamics of the tumor immune microenvironment, and provides a theoretical basis for the clinical translation of combination chemotherapy and immunotherapy targeting the NRP1-autophagy axis." (PMID 41948345, 2026). "Similarly, a PL3-derived linear peptide achieves precise NRP-1 targeting exclusively through uPA-mediated proteolytic cleavage, effectively minimizing off-target accumulation while maintaining tumor penetration capability." (PMID 41531498, 2026). "NRP1 significantly influences tumor development and incidence." (PMID 40277760, 2025). "Understanding the connection between EZH2 and NRP1 and how their interaction drives tumor growth and therapeutic resistance through autophagy regulation could provide novel insights for therapeutic strategies." (PMID 40314246, 2025). "NRP1 expression was detected intensely and diffusely in MB tissue in most tumor vessel endothelium." (PMID 40805120, 2025). "Thus, NRP1 is not only a key mediator of tumor immunomodulation but also plays a central role in angiogenesis." (PMID 40257955, 2025). "Such exosomes load with NRP1 and other pro-tumor proteins, such as MCAM and PTK2." (PMID 40908470, 2025).
tumor (continued). "Treg cells help tumor cells to escape killing cytotoxic CD8+ T cells causing an immunosuppressive effect; in patients with PAAD, tumor microenvironment (TME) and poor prognosis have correlated with high expression of NRP1, indicating more CD8+ T cells." (PMID 40277760, 2025). "Metabolomics can identify specific metabolic signatures that reflect NRP1’s role in tumor biology." (PMID 40277760, 2025). "Targeting NRP1 may help restore immune responses and inhibit angiogenesis, offering a promising strategy for both immunotherapy and anti-tumor treatment." (PMID 40257955, 2025). "Additionally, CEND-1, a cyclic peptide targeting αV integrins and neuropilin-1, enhances drug delivery to tumor sites." (PMID 40075563, 2025). "Additionally, NRP-1 contributes to tumor growth by modulating the tumor microenvironment, which results in the increased organization of fibronectin fibrils." (PMID 40430075, 2025). "These genetic alterations can increase NRP1 signaling, promoting tumor growth and survival." (PMID 40277760, 2025). "The modulation of NRPs with specific inhibitors seems to be a promising approach for cancers therapy due to its role in angiogenesis, tumor progression, and fibrosis, with potential treatments including NRP-1 antagonists, CAR-T cell therapy, and siRNA delivery using polymeric nanoparticles." (PMID 40430075, 2025). "Therefore, it seems that inhibiting NRP-1 using polymeric nanoparticles to deliver specific siRNAs inhibits tumor growth or reduces proliferation, making it a promising approach for treating of PDAC." (PMID 40430075, 2025). "When VEGFA binds to NRP1, it encourages Ras homolog family member A (RhoA) activation, which subsequently contributes to the degradation of cyclin-dependent kinase inhibitor (p27kip1), which in turn encourages the proliferation of tumor cells." (PMID 40277760, 2025). "G0 serves as the fluorophore and is conjugated with a tumor-targeting peptide for NRP1." (PMID 40048021, 2025). "Recently, there has been a great deal of interest in NRP1 as a mediator of tumor development and progression since it was observed to be extensively expressed in tumor vasculature, where NRP1 over-expression is accompanied by tumor progression and poor clinical outcome." (PMID 40277760, 2025). "Therefore, probably due to both reduced Nrp-1 expression and reduced Treg cell numbers, tumor growth was reduced in these mice." (PMID 40977681, 2025). "iRGD-modified nano-delivery systems based on marine sulfated polysaccharides exhibited significantly improved tumor targeting and cellular internalization, with the iRGD peptide facilitating deeper tissue penetration through neuropilin-1 (NRP-1) receptor-mediated transcytosis." (PMID 41155895, 2025). "In addition to directly encouraging tumor development and migration, NRP1 also modifies the tumor microenvironment by interacting with integrins and altering the extracellular matrix to affect tumor growth." (PMID 40277760, 2025). "While our study provides novel insights into the expression of NRP1 in MB and its possible association with TAMs, the TME, and tumor vascular proliferation patterns, it is worth noting that our analyses were performed using FFPE tissue, which is prioritized for diagnostic purposes." (PMID 40805120, 2025). "The role of NRP-1 in tumor metastasis appears to be multifaceted." (PMID 40430075, 2025). "Notably, EZH2 enhanced the neuropilin-1 (NRP1) level by binding to the NRP1 promoter, thereby promoting tumor proliferation and irinotecan resistance through autophagy inhibition." (PMID 40314246, 2025). "These modifications can influence NRP1’s function in tumor progression and response to therapy." (PMID 40277760, 2025). "Additionally, NRP1 promotes tumor cell survival and progression by interacting with the hypoxia response and microRNAs." (PMID 40299539, 2025).